DTNBP1 (dystrobrevin binding protein 1)
Diseases named in the same sentence as DTNBP1 in open-access papers (continued):
Sharing a sentence is not in itself a finding about the gene and the disease.
schizophrenia (continued). "It has been suggested that there is a reduced expression of DTNBP1 in the frontal cortex and hippocampal formation of schizophrenia patients." (PMID 19445674, 2009). "In the case of schizophrenia, a population-based analysis has revealed four genes, DAAO (DAO), DAOA, DTNBP1 and NRG1, to be associated with the schizophrenia." (PMID 19379523, 2009). "Another potentially valuable gene marker for schizophrenia is the dystrobrevin-binding protein 1 (DTNBP1), also known as dysbindin." (PMID 19128481, 2009). "Although preliminary, our results add to the growing body of research that genetic variation in DTNBP1 alters schizophrenia liability, possibly by affecting cognition." (PMID 17445278, 2007). "Reduced DTNBP1 expression has been reported in the dorsolateral PFC (DLPFC) in postmortem brain tissue of patients with schizophrenia." (PMID 17445278, 2007). "Expanding the analysis to include additional schizophrenia-associated genes such as DISC1, NRG1, COMT, and DTNBP1 could provide a more comprehensive view of the genetic risk factors relevant to our population." (PMID 40977746, 2025). "Furthermore, investigations of saliva and postmortem brain samples from schizophrenia patients have revealed increased levels of 5mC in the DTNBP1 promoter, suggesting the potential role for 5mC on DTNBP1 in schizophrenia." (PMID 38203806, 2024). "Furthermore, elevated methylation of the DTNBP1 gene in both schizophrenia patients and their first-degree relatives was partially reversed by antipsychotic treatments." (PMID 39678047, 2024). "In addition, increased methylation of the DTNBP1 gene, observed in both schizophrenia patients and their first-degree relatives, was partially reversed with antipsychotic treatment." (PMID 39678047, 2024). "Additionally, DTNBP1 plays a role in schizophrenia by regulating neurotransmission through the modulation of N-methyl-D-aspartate receptors (NMDAR) and dopamine D2 receptors (DRD2)." (PMID 38203806, 2024). "In this context, Dystrobrevin Binding Protein 1 (DTBP1) gene, which encodes for Dysbindin (DYS), and the dopamine D2−like receptors (D2R and D3R) represent leading candidate susceptibility genes for schizophrenia." (PMID 37240042, 2023). "There is evidence to suggest that Dystrobrevin-binding Protein 1 (DTNBP1) may be involved in regulating neuronal growth and neurotransmission, contributing to the pathogenesis of schizophrenia as a result." (PMID 36980961, 2023). "In the post-mortem brain, presynaptic DTNBP1 is reduced in synaptic terminals of hippocampal formations, which may contribute to cognitive deficits commonly seen in schizophrenia." (PMID 35815020, 2022). "DTNBP1 expression level is significantly reduced in the brain of schizophrenia patients." (PMID 34997064, 2022). "DTNBP1 is also shown to be involved in initiating an immune response to environmental stimuli, which might explain the increased vulnerability of schizophrenia due to environmental impact in combination with genetic influence." (PMID 35815020, 2022). "It is also likely that malfunctioning of other DTNBP1 related processes could induce impairments that lead to the development of schizophrenia." (PMID 35815020, 2022). "Furthermore, they offer tantalising glimpses into mechanisms and putative target sites relating to DTNBP1/dysbindin-1A and how these concepts might generalize to a broader spectrum of developmental genes and regulatory proteins implicated in the pathobiology of schizophrenia spectrum psychosis." (PMID 32063853, 2019). "Sequence variation might be a mechanism by which the function of DTNBP1 differs between schizophrenia cases and controls." (PMID 32063853, 2019). "Other studies have also failed to report a relationship between DTNBP1 variants and general tests of cognitive ability in patients with schizophrenia and first-degree relatives compared to controls." (PMID 32063853, 2019).
schizophrenia (continued). "A recent study investigated four candidate genes (DTNBP1, NRG1, DAOA/G32, and DAAO) common to schizophrenia and schizotypy and found DTNBP1, SNPs, rs2619522, and rs760761 single nucleotide polymorphisms (SNPs) to be associated with a decrease in positive and paranoid schizotypy scores [62•]." (PMID 29577010, 2018). "Among the genes which may increase the susceptibility to schizophrenia and ASD is DTNBP1 (dysbindin)." (PMID 27134685, 2016). "DTNBP1 mRNA and protein expression are decreased in the hippocampus and dorsolateral prefrontal cortex of individuals with schizophrenia, while the DTNBP1 promoter is hypermethylated in the saliva and brain in individuals with schizophrenia." (PMID 27134685, 2016). "DTNBP1 is a major candidate gene for schizophrenia and has important roles in neural development." (PMID 27462430, 2015). "In addition, decreased gene expression of NRG1 and dystrobrevin binding protein 1 (DTNBP1) were shown to be lower in immortalized lymphocytes from patients with schizophrenia vs. controls before and after treatment with the antipsychotic olanzapine." (PMID 23805071, 2013). "All three sets of module genes include well-studied candidate genes for schizophrenia (e.g., DTNBP1), glutamate receptors (e.g., GRIN1), several genes located in the MHC region (e.g., HIST1H1A, HIST1H1C, HIST1H2AB, HIST1H2BB, HLA-E), and genes from the 14-3-3 protein family (e.g., YWHAQ, YWHAZ)." (PMID 23134571, 2012). "The debate of association between DTNBP1 and schizophrenia has not been settled and as of yet no global significance has been identified." (PMID 21789192, 2011). "In particular, negative symptoms in schizophrenia have been shown to be associated with several SNP of the DTNBP1 gene." (PMID 20846375, 2010). "Several studies have investigated the effect of DTNBP1 in the development of schizophrenia." (PMID 20846375, 2010). "Functional studies of DTNBP1 provide further evidence for its role in schizophrenia aetiology." (PMID 20615259, 2010). "Genetic variations in DTNBP1 are associated with cognitive functions, general cognitive ability and memory function, and clinical features of patients with schizophrenia including negative symptoms and cognitive decline." (PMID 18945333, 2008). "No genetic variation in or around the DTNBP1 exons and its control regions have so far been found to have a convincing role in causing schizophrenia." (PMID 17888175, 2007). "This may occur already in an early stage, since genetic variation in DTNBP1 has been associated with poor premorbid function in children developing childhood-onset schizophrenia, suggesting that DTNBP1 contributes to early neurodevelopmental impairment." (PMID 17445278, 2007). "In addition, post-mortem studies have shown that DTNBP1 expression is reduced in the hippocampus and prefrontal cortex of patients with schizophrenia, regions of the brain that are crucial for adequate cognitive functioning." (PMID 17445278, 2007). "To date, association between genetic variation in the DTNBP1 gene and intellectual functioning in unaffected relatives of patients with schizophrenia-spectrum disorders has not yet been studied." (PMID 17445278, 2007). "Abnormalities in the DTNBP1 pathway may lead to schizophrenia." (PMID 38203806, 2024). "In this mini-review, we will summarize evidence for the dysfunctions in dysbindin-1 (DTNBP1), a protein coding gene regularly implicated in schizophrenia as well as brain-derived neurotrophic factor (BDNF), and GABAergic circuit function in relation to schizophrenia." (PMID 35815020, 2022). "Interestingly, the hippocampus is an enriched region for DTNBP1 under normal conditions, and postmortem studies have shown a decreased level of DTNBP1 expression in the hippocampus of patients with schizophrenia, indicating that decreased DTNBP1 is a pathological condition in schizophrenia." (PMID 33679873, 2021).
schizophrenia (continued). "It is not known whether sex and DTNBP1 mutation impact the developmental GluN2B-GluN2A switch in the brain, thereby increasing risk for schizophrenia and/or ASD." (PMID 27134685, 2016). "However, most genetic analyzes and functional studies on DTNBP1 have focused on dysbindin-1A, whereas the functional role of other dysbindin isoforms in schizophrenia remains unclear." (PMID 27462430, 2015). "While many genetic studies could replicate the association of DTNBP1 with schizophrenia, others failed to confirm the finding of Straub and colleagues." (PMID 22580710, 2013). "Additionally, a few non-synonymous amino acid changes have been observed in its gene product, dystrobrevin binding protein 1, in the human population, but none of these have been definitively associated with schizophrenia." (PMID 19445674, 2009). "Moreover, the association between some clinical features of schizophrenia, such as its negative symptoms, and a risk haplotype of DTNBP1 has been demonstrated." (PMID 18945333, 2008). "In addition to cognition, DTNBP1 has recently been associated with high levels of negative symptoms in patients with schizophrenia; these findings are relevant in this context since negative symptoms and cognitive dysfunction are highly correlated." (PMID 17445278, 2007). "Glutamatergic neurotransmission in the hippocampus is important for memory formation, therefore reductions in DTNBP1 in the hippocampus of schizophrenia patients as observed by Talbot may disturb normal information processing and diminish synaptic plasticity in the hippocampus." (PMID 17445278, 2007). "Thus, genetic variation in DTNBP1 may impact on dopaminergic and glutamatergic systems in the PFC and hippocampus, thereby disturbing memory and cognition and increasing schizophrenia susceptibility." (PMID 17445278, 2007). "Changes in DTNBP1 expression are probably not caused by antipsychotic drug treatment but instead may reflect an increased genetic vulnerability for schizophrenia." (PMID 17445278, 2007). "However, even positive studies of European populations do not show any consistent DTNBP1 alleles or haplotypes associated with schizophrenia." (PMID 17888175, 2007). "As for MAM, a model with schizophrenia was studied to determine epigenetic changes around the Drd7 gene and showed differential DNA methylation in the co-factors DISC1, Syp, and Dtnbp1." (PMID 39997929, 2025). "Moreover, gene-associated studies showed a possible relationship between the risk of schizophrenia and some variants in genes related to dopamine signaling, i.e., catechol-O-methyltransferase (COMT), monoamine oxidase (MAO), dopamine transporter (SLC6A3), and dystrobrevin-binding protein 1 (DTNBP1)." (PMID 37899392, 2023). "Therefore, DTNBP1 plays an essential role in activity-dependent neurotransmitter release, and DTNBP1 downregulations or genetic variations may contribute to schizophrenia by decreasing the size of readily releasable pool of synaptic vesicles which regulates synaptic transmission." (PMID 35815020, 2022). "PPI behavioral deficits that were reversed by local infusion of BDNF in Dtnbp1 knockout mice with schizophrenia-like behavior underscores the importance of DTNBP1 in regulating BDNF secretion and its role in the development and treatment of schizophrenia." (PMID 35815020, 2022). "Since the hippocampus is also crucial in TLE pathologies characterized by deregulation of neuronal excitability, it is likely that DTNBP1 plays a key role in both TLE and schizophrenia." (PMID 33679873, 2021). "While genetic background does appear to be an important factor in determining whether specific schizophrenia-related phenotypes are reported for the sdy mouse, memory impairment is a consistent phenotypic trait of DTNBP1-deficient mice irrespective of the mouse strain adopted." (PMID 27725886, 2016). "After adjusting for age and PMI, DTNBP1, COMT and DRD2 were found to be differentially methylated between the two schizophrenia subgroups." (PMID 24399042, 2014).
schizophrenia (continued). "The interactions among DTNBP1, DLG4 and EXOC4 are present in various brain tissues, such as prefrontal cortex and temporal lobe, which are known to be related to schizophrenia etiology." (PMID 19379523, 2009). "Mice lacking Dtnbp1 showed behavioral deficits similar to human patients suffering from schizophrenia." (PMID 35815020, 2022). "The primary analyses did not demonstrate associations between schizophrenia and any of the 32 studied DAOA, DAO, PPP3CC, and DTNBP1 SNPs." (PMID 23497497, 2013). "Among the many genes which may promote development of schizophrenia, DTNBP1 (dystrobrevin binding protein 1) remains among the top candidates and is hence among the most intensively investigated." (PMID 21390302, 2011). "They found significant evidence for a gene x environment interaction in V-akt murine thymoma viral oncogene homolog 1 (AKT1), brain-derived neurotrophic factor (BDNF), dystrobrevin binding protein 1 (DTNBP1), and glutamate receptor metabotrophic (GRM) genes in developing schizophrenia." (PMID 20046382, 2009). "The results suggest that the DTNBP1 gene contribution to schizophrenia must be rare or absent in our sample." (PMID 17888175, 2007). "Moreover, DTNBP1 and RGS4 have been reported to be differentially expressed in postmortem brain samples of individuals with schizophrenia." (PMID 16033310, 2005). "The inclusion of scores from questionnaires about negative symptoms or other clinical features of schizophrenia may clarify the role DTNBP1 plays in brain function in schizophrenic patients." (PMID 21789192, 2011). "Since reduced expression of dysbindin-1 has been observed in postmortem brains of patients with schizophrenia, the sandy (sdy) mouse, which has a deletion in the Dtnbp1 gene and expresses no dysbindin-1 protein, could be an animal model of schizophrenia." (PMID 18945333, 2008). "While it is not yet known exactly how DTNBP1 regulates the functionality of different neural circuits in brain regions involved in schizophrenia, more studies are necessary to identify whether such a circuit change contributes to its role in the pathogenesis of schizophrenia." (PMID 35815020, 2022). "However, a follow-up study failed to report changes in NRG1, DTNBP1, or GNAO1 in patients with schizophrenia vs. controls." (PMID 23805071, 2013).
cognitive deficits (12 papers, 2011 to 2024). "Furthermore, the DTNBP1 genotype is linked to cognitive deficits, and genetic variations in dysbindin-1 reportedly correlate with the cognitive response to antipsychotic drugs." (PMID 35682647, 2022). "Several studies have explored the association between DTNBP1 and positive symptoms, negative symptoms, depression symptoms, anxiety symptoms, and cognitive deficits." (PMID 32581860, 2020).
Hermansky-Pudlak syndrome (8 papers, 2010 to 2022). Hermansky-Pudlak syndrome (HSP) is a multi-system disorder characterized by oculocutaneous albinism, bleeding diathesis and, in some cases, neutropenia, pulmonary fibrosis, or granulomatous colitis. "Homozygous missense point mutations in DTNBP1 have been found in patients with Hermansky-Pudlak syndrome (HPS [MIM 203300]), an autosomal recessive disease with features that include albinism, pulmonary fibrosis, and bleeding." (PMID 22480366, 2012). "Dysbindin, a cytoplasmic protein encoded by DTNBP1, has been genetically linked to the Hermansky-Pudlak syndrome (HPS)." (PMID 20174469, 2010). "A disease association for DBNDD1 is not identified yet, but mutations in DTNBP1 are responsible for the Hermansky-Pudlak syndrome 7, which is characterized by oculocutaneous albinism, prolonged bleeding, and pulmonary fibrosis." (PMID 27034888, 2016). "The targeted deletion of the Dtnbp1 gene produced by the IMPC recapitulates the main features of Hermansky-Pudlak syndrome (HPS), a rare autosomal recessive genetic disorder affecting roughly 1/500,000 individuals worldwide, but disproportionately present in 1/1800 people in Puerto Rico18,19." (PMID 31371754, 2019).
Anxiety (7 papers, 2010 to 2024). Intense feelings of nervousness, tension, or panic often arise in response to interpersonal stresses. "It is also suggested that a common underlying molecular defect involving DTNBP1 contribution to the development of anxiety and stress-related disorders may involve changes in glutamatergic neurotransmission or DA-ergic function." (PMID 27725886, 2016). "It is possible that DTNBP1 variation affects a common pathway involved in anxiety and addictive disorders." (PMID 20615259, 2010). "In previous studies, analyses of DTNBP1 tag SNP (e.g., rs1011313) and haplotypes found no conclusive evidence of any association with anxiety or depression disorders." (PMID 32581860, 2020).
bipolar disorder (6 papers, 2011 to 2022). A disorder of the brain that causes unusual shifts in mood, energy, activity levels and the ability to carry out day-to-day tasks. "Large genetic case–control association studies of European, Korean, and multiplex Ashkenazi Jewish family samples have shown a linkage of DTNBP1 with bipolar disorder." (PMID 22580710, 2013).
psychosis (6 papers, 2007 to 2022). "In this study, we report association between genetic variation in the DTNBP1 gene and IQ measures in patients with first-episode psychosis, unaffected siblings, and unrelated control subjects." (PMID 17445278, 2007). "In biological terms, over-activity of the mesolimbic dopamine pathway has been suggested as a contributor to the positive symptoms of psychosis including delusions and hallucinations; a number of genes in the dopamine pathway including COMT and DTNBP1 showed association with risk of psychosis." (PMID 23638040, 2013).
cognitive decline (3 papers, 2008 to 2021). "However, genes encoding, dystrobrevin-binding protein 1 (DTNBP1), brain-derived neurotrophic factor (BDNF), catechol-O-methyl transferase (COMT) and apolipoprotein E (APOE), have demonstrated a repeated association with cognitive decline." (PMID 34679354, 2021).
Hermansky-Pudlak syndrome type 7 (3 papers, 2007 to 2020). "In addition, DTNBP1 has also been implicated in Duchenne muscular dystrophy and in Hermansky-Pudlak syndrome type 7 (HPS-7)." (PMID 17888175, 2007). "Deletion of dystrobrevin binding protein 1 has been linked to Hermansky-Pudlak syndrome type 7 (HPS-7), a rare disease characterized by oculocutaneous albinism and retinal dysfunction." (PMID 32132582, 2020).
Duchenne muscular dystrophy (2 papers, 2012 to 2013). Duchenne muscular dystrophy (DMD) is a neuromuscular disease characterized by rapidly progressive muscle weakness and wasting due to degeneration of skeletal, smooth and cardiac muscle. "Moreover, DTNBP1 has been connected with autistic features observed sometimes in patients with Duchenne muscular dystrophy." (PMID 23324214, 2013). "Finally, DTNBP1 has been connected with autistic features observed sometimes in patients with Duchenne muscular dystrophy (DMD [MIM 310200])." (PMID 22480366, 2012).
hepatocellular carcinoma (2 papers, 2022 to 2023). A malignant tumor that arises from hepatocytes. "A higher DTNBP1 level is associated with shorter overall survival (OS), and a lower DTNBP1 level reduces cell proliferation and induces apoptosis in hepatocellular carcinoma cell lines." (PMID 37569304, 2023). "First, we analyzed the differentially expressed genes in TCGA dataset by using Edge R and found that DTNBP1 expression was upregulated in the hepatocellular carcinomas." (PMID 34997064, 2022).
lung carcinoma (2 papers, 2020 to 2023). "DTNBP1 gene expression was significantly increased in a variety of cancers, including acute myeloid leukemia (AML), breast cancer, colon cancer, liver cancer, lung cancer, ovary cancer, pancreatic cancer, rectal cancer, renal cancer, skin cancer, thyroid cancer, and uterine cancer." (PMID 37569304, 2023).
Auditory hallucination (1 paper, 2025). Perception of sounds without auditory stimulus. "Evidence suggests that the C allele of CCK-AR, the FOXP241 polymorphism, and the DTNBP1-rs423616740 variant are associated with a higher risk of auditory hallucinations in SCZ patients." (PMID 39465687, 2025).